TNF (tumor necrosis factor)
Diseases named in the same sentence as TNF in open-access papers (continued):
Sharing a sentence is not in itself a finding about the gene and the disease.
lymphopenia (continued). "Muscle-derived IL-6, one of the myokines with anti-inflammatory properties, inhibits TNF production and stimulates the production of IL-1ra and IL-10 as well as cortisol production, leading to lymphopenia and neutrocytosis." (PMID 36077525, 2022). "The severe group exhibited lymphopenia, especially in T-cell cytopenia, and hyper-cytokines, notably increased TNF-α and IL-6." (PMID 35573725, 2022). "Asymptomatic carriers exhibited higher N-specific IgG4/IgG1 ratio and higher RBD-specific/N-specific IgG1 while symptomatic patients exhibited increased neutrophil counts and lymphocytopenia as well as higher TNF-α, IL-2, IL-8, and IL-12p70." (PMID 35685940, 2022). "Next, there is older evidence from other clinical scenarios suggesting that multiple cytokines (IL-1, IL-6, TNF-α) are involved in generating lymphopenia by inducing apoptosis." (PMID 36676656, 2022). "Within the first hours following injection, while still normoglycemic, lymphopenia and pro-inflammatory cytokine secretion were observed, particularly tumor necrosis factor (TNF)-α." (PMID 36548717, 2022). "T cells reduction in the blood is also a contribution of mechanisms such as inflammatory cytokine milieu, which is why lymphopenia has a correlation with TNF-α, IL-6, and IL-10." (PMID 33716737, 2021). "This hypercytokinemia, initially named “cytokine storm”, is associated with high levels of circulating tumor necrosis factor (TNF) and interleukin-6 (IL-6), profound peripheral blood lymphopenia and chemoattraction of mononuclear cells within the lungs." (PMID 34088975, 2021). "According to numerous publications the patients tended to have lymphopenia, higher infection-related biomarkers and several elevated inflammatory cytokines [i.e., tumor necrosis factor alpha (TNF-α), interleukins IL-2R and IL-6]." (PMID 32612613, 2020). "Both lymphopenia and T cell exhaustion were directly correlated with the increase in the levels of IL-6, IL-10, and TNF alpha and with disease severity." (PMID 33072103, 2020). "Compared with severe and moderate patients, lymphocytopenia occurred in 85.71% critically ill patients, and serum IL-2R, IL-6, IL-8, TNF-α, LDH, and cTnI were also increased in 71.42%, 83.33%, 57.14%, 71.43%, 100% and 42.86% in critically ill patients." (PMID 32788884, 2020). "Boosting Th1-mediated inflammatory responses with PD-1 blockade, administrating steroids or anti-tumor necrosis factor-alpha agents to overcome immune-related adverse events and lymphopenia are among the potential mechanisms." (PMID 33213414, 2020). "Infection with EBOV first causes a significant inflammatory response and lymphoid cell apoptosis (most likely due to release of Tumor Necrosis Factor-α (TNF-α)), which leads to lymphopenia and suppression of effective adaptive immune response." (PMID 27223296, 2016). "Compared with controls, acute UCM was associated with mild lymphopenia, splenomegaly, and high levels of IFN-γ, tumor necrosis factor-α, and IL-10, which normalized in convalescence." (PMID 26335932, 2015). "Some studies suggest a potential link between lymphopenia and elevated levels of IL‐10, TNF or IL‐6, which may act directly on lymphocytes or indirectly via other cell lineages (e.g. neutrophils and DCs)." (PMID 41163794, 2025). "This is biologically plausible, as neutrophils and monocytes produce cytokines such as IL-1, IL-6, and TNF-α, which stimulate osteoclastogenesis, while lymphopenia may reflect diminished osteoprotective T-cell activity." (PMID 41140653, 2025). "Interestingly, TNF-α-mediated apoptosis of CD4+ T cells has also recently been shown to contribute to SARS-Co-V2-induced lymphopenia." (PMID 38256231, 2024). "Thus, TNF-α appears to be a major cytokine involved in the pathogenesis of the characteristic lymphocytopenia during CSFV infections." (PMID 38393074, 2024).
lymphopenia (continued). "Further analysis revealed activation of multiple cell apoptosis pathways (e.g., granzyme/perforin-, FAS- and TNF-induced apoptosis) may be responsible for lymphopenia." (PMID 37848421, 2023). "Severe mycobacteria antigen stimulation induced persistent production of IFN-γ and TNF-α, which may impact hematopoiesis and lead to lymphopenia." (PMID 36743311, 2023). "Lymphopenia reflect adverse inflammatory, and the increase of inflammatory mediators such as tumor necrosis factor and interleukin 1β may reduce levels of circulating T cells." (PMID 36920980, 2023). "Several studies have reported cellular and molecular changes related to immunity include lymphopenia, neutrophilia, inflammatory cytokines, IL‐6, TNF‐α granulocyte colony‐stimulating factor (G‐CSF) and monocyte chemoattractant protein‐1 (MCP1) in severe COVID‐19 patients." (PMID 38156391, 2023). "Moreover, it has been reported that tumor secretion of TNF-α and IL-10 leads to lymphopenia and lymphocyte dysfunction." (PMID 37190296, 2023). "There is evidence to support that TNF-α may be a driving force in peripheral lymphocyte apoptosis further contributing to lymphopenia." (PMID 35359679, 2022). "Moreover, it is often related to alterations in immune activity, including increased levels of pro-inflammatory cytokines (e.g., IL-6 and TNF-α), lymphopenia, and T cell depletion." (PMID 36359845, 2022). "Results demonstrate very early lymphopenia and TNF-α production." (PMID 36548717, 2022). "The immunological hallmarks comprise lymphopenia and a flurry of active molecules which gives rise to the so-called “cytokine storm”, largely dominated by interleukin (IL)-6 and tumor necrosis factor (TNF)-α." (PMID 34078447, 2021). "In severe cases, induced expression of inflammatory cytokines (especially IL-6, TNF-α) can shift from local to systemic inflammation through dysregulation of immune pathways and immune cell distribution (lymphopenia, T-cell exhaustion, increasing counts of macrophages and neutrophils)." (PMID 34858428, 2021). "Lymphopenia may contribute to insufficient production of chemokines with anti-neoplastic activity such as interferon-γ, tumor necrosis factor, or interleukin-1." (PMID 34422649, 2021). "More severe cases, generally defined by hospitalization, intubation, and/or mortality, can also exhibit dyspnea, lymphopenia, and hypoalbuminemia with concomitant increases in the proinflammatory cytokines interleukin 6 (IL-6), tumor necrosis factor alpha (TNF-α), and interleukin 1 beta (IL-1ß)." (PMID 33042114, 2020). "Interstitial pneumonia and lymphopenia, driven by high levels of pro-inflammatory cytokines including interleukin 6 (IL-6) and tumor necrosis factor alpha (TNF-α), C-X-C ligand 10 (CXCL10), C-C motif ligand 2 (CCL2) and CCL3, may be seen in severe cases." (PMID 33302366, 2020). "The presence of high levels of IFN has been linked to the depletion of B-and T-cells from the blood of CSFV-infected pigs and IFN, in combination with TNFα, could contribute to the lymphopenia observed during acute ASF." (PMID 27043071, 2016). "In addition to IFN-γ, the upregulation of tumor necrosis factor-alpha (TNF-α) during the development of FIP has been reported to result in lymphopenia." (PMID 25512064, 2014). "Furthermore, Ripk1ΔCD4Casp8 ΔCD4 and Ripk1ΔCD4Tnfr1−/− double-knockout mice rescued the peripheral T cell lymphopenia, revealing that RIPK1-deficient naive CD4+ and CD8+ cells and FoxP3+ regulatory T cells specifically die from TNF- and caspase-8-mediated apoptosis in vivo." (PMID 38734851, 2024). "We found that persistent mycobacteria antigen stimulation induced excessive expression of IFN-γ and TNF-α, which promoted myeloid differentiation, repressed lymphoid commitment, and reduced the proliferation activity of LK cells, ultimately leading to peripheral lymphopenia." (PMID 36743311, 2023).
lymphopenia (continued). "However, upon binding to TNF-α, Treg function is suppressed but their anti-proliferative function seems intact, which is hypothesized to explain the paradoxical PB lymphopenia despite dysfunctional Tregs." (PMID 37161980, 2023). "From an immunological point of view, the lymphopenia could depend on the possible dysfunctional activation of dendritic cells already mentioned and the high concentration of cytokines such as TNF-α, IL-6, and IL-10, which act as negative regulators of the proliferation and survival of T lymphocytes." (PMID 33324414, 2020). "However, this might be an indirect effect since splenic lymphopenia has also been observed in other ECTV lethal infections where the host ability to mount an efficient TNF and chemokine response is intact." (PMID 29724993, 2018). "However, the mechanisms behind PB lymphopenia and its correlation with TNF-α levels remain unclear." (PMID 40205574, 2025). "Pro-inflammatory cytokines (IL-6 and TNF-α) have been shown to suppress TSH secretion and promote lymphopenia, suggesting a potential link between endocrine and immune dysregulation." (PMID 41375681, 2025). "Similarities included resolution of lymphopenia and neutrophilia and a rapid decrease in the serum concentrations of CRP, TNF-α, IL-6, IFN-γ, IL-10, TNFR-1, and IP-10 following treatment with Allocetra-OTS." (PMID 37600829, 2023). "Propranolol was also reported to control acute ischemic stroke patients with lymphopenia through its role in enhancing TNF-α, IL-10, and TNF-α/IL-10." (PMID 35893792, 2022). "Hematopoietic alterations are characterized by lymphopenia, thrombocytopenia, thromboembolism, and increased plasma levels of inflammatory cytokines and chemokines (i.e., IL-6, CCL2, TNF-α)." (PMID 34944747, 2021). "The immunological profile is characterized by the reduction of CD4+ and CD8+ T-lymphocytes (lymphopenia), decreased level of CD4+cell expression of INF-γ and increased cytokines Interleukin-6 (IL6), IL-10 and tumor necrosis factor-alpha (TNFα)." (PMID 32974295, 2020). "Parallels seen in late-stage disease mice include: high viral loads (RNAemia), elevated AST and ALT, elevated neutrophils, lymphopenia, and increases in IL-10, IL-6, IFN-γ, CCL2, CCL5, and TNF-α." (PMID 31790513, 2019). "We found that children recruited with acute UCM presented with lymphopenia and splenomegaly and higher than normal levels of IFN-γ, TNF-α, and IL-10, which normalized 1 month into convalescence." (PMID 26335932, 2015). "This manifests itself in neutrophilia, lymphopenia, and an exaggerated release of a myriad of different cytokines, predominantly interleukins IL-1, -2, -6, -8, -10, -18, interferon (IFN)-γ, tumor-necrosis-factor (TNF)-α and monocyte chemoattractant protein-1 (MCP-1)." (PMID 36557315, 2022). "In patients with severe disease, laboratory values taken at primary infection showed signs of lymphopenia and systemic inflammation, including increased concentrations of C-reactive protein (CRP), IL-6, and TNF, and some of these inflammatory markers remained perturbed at 6-month follow-up." (PMID 35078982, 2022). "Profiles of single-cell RNAseq from patient blood samples confirm the suppression of B- and T-cells (lymphopenia), T-cell exhaustion, and TNF/IL1β–driven inflammation signature not typical to all mortalities in this study." (PMID 34335605, 2021). "Lymphopenia is a common feature and negative prognostic factor in cats with FIP, caused by increased apoptosis of B and T cells induced by tumor necrosis factor alpha expression." (PMID 34835034, 2021). "Immune dysregulation in adults with respiratory disease is characterized by lymphopenia (specifically NK cells, CD4 T lymphocytes and B lymphocytes) and sustained production of pro-inflammatory cytokines, such as tumor necrosis factor (TNF)-α and interleukin (IL)-6." (PMID 32630212, 2020).
lymphopenia (continued). "Therefore, T lymphopenia in the Ripk1−/−Ripk3−/−Tradd−/− mice is counterintuitive, given that thymocytes from these TKO mice are completely resistant to TNFα-induced apoptosis." (PMID 30741936, 2019). "IL-7 could reverse impaired hematopoiesis and lymphopenia by decreasing IFN-γ and TNF-α levels." (PMID 36743311, 2023). "Significant among them are neutrophilia, neutrophil-to-lymphocyte ratio (NLR), lymphopenia, inflammatory markers like C-reactive protein (CRP), and cytokines including interleukin-6 (IL-6), interleukin-8 (IL-8), interleukin-18 (IL-18), interferon-α (IFN-α), and tumor necrosis factor (TNF)." (PMID 35464560, 2022). "Lymphopenia is mediated by the overmentioned inflammatory cytokine milieu (especially rich in IL-6, IL-10, and TNF-α), via lymphocyte sequestration into lymphoid tissue and endothelia by IFN-I and TNF-α or by extensive cell death triggered by IL-6 and Fas-FasLigand signaling." (PMID 33996683, 2021). "Interestingly, TNFα expression can also initiate lymphocytic apoptosis via a complex interplay between FAS receptor and TNF receptor (TNFR)-II signaling, which we speculate may have a role in early lymphopenia and immunosuppression post-TBI." (PMID 34640381, 2021). "Besides, a study showed that severe infection by SARS-CoV-2 could create lymphopenia with decreased CD4+ and CD8+, but interestingly, there is no decrease in lymphocytes B. In summary, there is an increase in cytokines IL6, IL2R, IL10, TNFα, and MCP-2 production and a decrease in IFN-γ production." (PMID 34078305, 2021). "Interestingly, the elevated IL-10 in the serum was correlated with the appearance of lymphopenia during FMDV infection but not IL-6, IL-2, IL-17, IL-18, IL-1β, TNF-α, IFN-α/β, TGF-β, and CXCL1." (PMID 34960627, 2021). "Interestingly, IL-10 but not TNF-α in the serum from infected mice was upregulated following FMDV infection, and the elevated levels of IL-10 coincided with the occurrence of lymphopenia in this study." (PMID 34960627, 2021). "Thus, it is tempting to speculate that patients with lymphopenia and/ or HLA-DRB1*07 positive patients should receive 3rd line treatment with TNF-α inhibitors early in disease course without first trying 1st and 2nd line treatments." (PMID 37161980, 2023). "The significant difference between SLE patients and HCs observed upon stimulation with the superantigen SEB, regarding IFNγ, IL17, and TNFα may indicate that leukocytes are generally dysfunctional in the SLE patients, also in those without lymphopenia, and unable to respond properly to the stimuli." (PMID 29499037, 2018).
AIDS (143 papers, 1990 to 2026). A syndrome resulting from the acquired deficiency of cellular immunity caused by the human immunodeficiency virus (HIV). "Elevated levels of pro-inflammatory cytokines like IL-6, IL-1β, and TNF-α are associated with an increased risk of non-AIDS-related comorbidities such as cardiovascular diseases, neurocognitive disorders, and certain cancers." (PMID 40184131, 2025). "The increased production of cytokines such as IL-6, IL-1 and TNF-alpha in monocytes is associated with non-AIDS comorbidities in PLWHIV." (PMID 40331967, 2025). "Tumor necrosis factor (TNF) and interleukin 6 (IL-6) represent pro-inflammatory cytokines associated with AIDS progression and were quantified using a cytometric bead array." (PMID 39459974, 2024). "IL-10 has been shown to block HIV-induced TNF-α and IL-6 secretion and inhibit HIV replication, and a cohort study of 51 people with HIV suppressed on ART demonstrated decreasing plasma IL-10/TNF-α ratio to be associated with AIDS progression." (PMID 38019897, 2023). "Inflammation is associated with untreated HIV-1 infection, and high baseline levels of IL-6, IL-10, and TNF-α are associated with increased risks of AIDS-defining events." (PMID 34983415, 2022). "In line with observations of CSF cytokines, it was reported that higher secretions of IFN-γ and TNF-α by peripheral CD4+ T cells were associated with improved survival of HIV/AIDS patients with cryptococcal meningoencephalitis." (PMID 36557672, 2022). "Further, higher mortality rates occurred in PLWH with low levels of Zn2+, and Zn2+ deficiency and increased levels of tumor necrosis factor-α (TNF-α) were found in people with AIDS." (PMID 32326317, 2020). "This is in accordance with the intensity of the risk factor shown by DM2 (around ×3), which is much lower than the risk factor for immunosuppression by anti-TNF or AIDS (around ×100), where a clear phenotype can be seen." (PMID 31681334, 2019). "During HIV chronic infection, the presence of IL-6, IL-10, and TNF-α are associated with poor prognosis and progression to AIDS because they contribute to the chronic activation of B-cells." (PMID 30337929, 2018). "Earlier studies have clearly shown that increased levels of TNF-α and IL-10 in the plasma is associated with the evolution of AIDS-diseases." (PMID 30464243, 2018). "In a recent study, poor survival in a cohort of AIDS patients with CM was associated with decreased monocyte production of TNF-α and IFN-γ in whole blood stimulated with LPS." (PMID 28486489, 2017). "TNF-alpha (TNF-a) has been recently associated with an increased risk of non-AIDS defining conditions." (PMID 26641655, 2015). "Many of the immune mediators expressed at high levels in AIDS patients were also up-regulated in patients with CD (TNF-α, IL-1β, and IFN-γ) and have been implicated in the pathogenesis of CD." (PMID 26475133, 2015). "Preliminary data suggest a central role for TNFα in HIV-associated non-AIDS disease but it remains to be determined to what extent other pro-inflammatory cytokines, perhaps acting via TNFα, are involved." (PMID 24133492, 2013). "The risk factors for dissemination are T cell deficiencies such as AIDS, organ transplantation, and pregnancy, as well as treatment with tumor necrosis factor alpha (TNF-α) inhibitors." (PMID 23006927, 2012). "During chronic HIV-1 infection, many plasma proteins and activation markers, such as neopterin, TNF-α and sCD14, are associated with progression towards AIDS." (PMID 23056251, 2012). "In HIV/AIDS patients, autoantibodies and the associated release of tumor necrosis factor-α have been revealed to reduce proteins activity." (PMID 22347662, 2011). "Reported risk factors for PDH include: AIDS, primary immunodeficiency, immunosuppressive medications such as corticoids, methotrexate, TNF-alpha inhibitors, and advanced age." (PMID 21727649, 2011).